MYC (MYC proto-oncogene, bHLH transcription factor)
Diseases named in the same sentence as MYC in open-access papers (continued):
Sharing a sentence is not in itself a finding about the gene and the disease.
tumor (continued). "Oncogenic MYC alters global transcriptional programs to drive stem cell traits in cancer, while concomitantly downregulating tumor suppressor genes and cell cycle regulators." (PMID 36207293, 2022). "In a recent RNA‐seq study, both PLK1 and MYC oncogenes were found overexpressed in two well‐established cOSA cell lines, suggesting a potential implication of this signalling axis in this tumour." (PMID 36054794, 2022). "For example, the well-known downregulated let-7 family plays tumor-suppressive roles in OC by targeting oncogenes, such as c-MYC, HRAS, and KRAS, and cell cycle regulators." (PMID 35549643, 2022). "The presence of CIP2A and MYC at the NPC signifies that the tumor suppressive activity of PP2A-B56α is likely inhibited, potentially promoting oncogenic signaling though a PP2A-B55α-MYC axis." (PMID 35118387, 2022). "This protein tends to be localized in the nucleus and binds the c-MYC promoter, functioning as a tumor suppressor." (PMID 35078505, 2022). "Plotting of RT-qPCR results versus normalized RNA-seq read counts confirmed the identification of high and low tumor profiles with respect to MYC expression." (PMID 36139061, 2022). "By comparing gene expression of Smarcb1-negative tumor clusters (TCs) of all three MYC subtypes, we identified localization-specific tumor markers." (PMID 35318328, 2022). "Despite having a half-life in plasma of approximately 1.5 hours, MYCMI-7 treatment reduced tumor volume significantly in all three models and increased overall survival in two of three models, with exception of MYC/BCL-XL–driven AML." (PMID 36874405, 2022). "Cluster 1 exhibited a poor prognosis and was characterized by decreases in the HIPPO-, MYC-, NOTCH-, NRF1-, TGF-beta-, PIK3-, and RAS-associated tumor pathways." (PMID 36175504, 2022). "For this purpose, we performed scRNA-seq analyses from murine tumor material (five ATRT-MYC, three MYC spinal, three eRT samples and two ATRT-SHH)." (PMID 35318328, 2022). "Proto-oncogene c-MYC plays an important role in the carcinogenic transformation of normal cells and tumor proliferation." (PMID 36367775, 2022). "Authors here show that the oncogene MYC plays a pivotal role in suppressing anti-tumour immunity via directly regulating the transcription of interferon signalling genes." (PMID 36323660, 2022). "More broadly, tumor cells that over-express MYC are very vulnerable to GLS, because they rely largely on glutamine oxidation to refill the TCA cycle, even under hypoxic circumstances." (PMID 35204484, 2022). "The MYC expression distribution in pan-cancer cell lines and the clinical tumor–node–metastasis (TNM) stage of MYC were shown in the CCLE." (PMID 35847359, 2022). "In this study, we found that the cells mediating the tumor-killing effect had a higher infiltration abundance in the MYC signaling activation group." (PMID 36299592, 2022). "Deregulation of Myc transcription in Eμ-Myc transgenic mice occurs stepwise exceeding physiological levels of MYC in pre-tumor cells." (PMID 36611833, 2022). "The results showed that GSTM2 expression was associated with the activities of signatures including cellular response to hypoxia, tumor proliferation signature, apoptosis, DNA repair, G2M checkpoint, MYC targets, TGFB, DNA replication, and degradation of ECM." (PMID 36263204, 2022).
tumor (continued). "For the MYC gene, although MYC overexpression increases the probability of tumor occurrence, the MYC gene itself plays an important role in cell proliferation and anti-apoptosis." (PMID 35369066, 2022). "O-GlcNAcylation increases the stability of c-MYC, which promotes the expression of genes related to glycolysis and Gln catabolism, providing energy to tumor cells." (PMID 36699061, 2022). "MYC expression was also significantly higher in TAc than in the matched tumor samples and in TAc than in Ctrl samples." (PMID 36140779, 2022). "Previous studies have found that targeting CDK9 in cancers can inhibit oncogenes (e.g. MYC) and reactivate tumor suppressor genes (e.g. CHD5)." (PMID 35394046, 2022). "MXD1 is a tumor suppressor and functions to compete with MYC for interacting with MAX to form a transcription repressor of the MXD1-MAX." (PMID 36167790, 2022). "Previous studies have in fact shown that a brief suppression of N-MYC is associated with an irreversible change in the cellular program and a two-fold decrease in oncogenic levels of MYC was sufficient to induce tumor regression." (PMID 35883689, 2022). "IHC results in subcutaneous tumor tissues also showed less cyclin E1 and c-MYC expression in INPP5F knockdown group." (PMID 34996491, 2022). "ER and PR target several oncogenes that are known to impact tumor cell metabolism including MYC and PI3K/AKT/mTOR that increase glucose transport, glycolysis, and lipid synthesis." (PMID 35406548, 2022). "Critically, we show that treatment with miR-138 mimics was able to reduce MYC expression and tumor growth in a well-established transgenic mouse model for MYC-driven HCC." (PMID 34937878, 2022). "This confirmed that, whereas the status of both genes was diploid in normal benign tissue (clone A), MYC amplification and PTEN loss were evident in altered benign (clone C) as well as tumour (clone F) clones." (PMID 35948708, 2022). "Again, administration of DZNep, which depleted EZH2 and MYC(N), markedly inhibited proliferation of all the tumor cells examined, while administration of the enzymatic inhibitor GSK126 largely exhibited minimal effect." (PMID 35013218, 2022). "Nonetheless, our data suggests that USP1 is a novel target for MYC-driven tumours and that this warrants further investigation." (PMID 36240066, 2022). "MYC has therefore been highlighted as a key therapeutic target for cancer therapy for a number of tumor types." (PMID 36874405, 2022). "Previous studies have shown that MYC downregulates several tumor-suppressive miRNAs, such as the miR-29 family." (PMID 36672841, 2022). "The low efficacy of anti-PD-L1 in MYC-elevated cancers is in part linked to suppression of MHC-I genes and low tumor immune cell infiltration in patient tumors and mouse models." (PMID 35760778, 2022). "Tumor cells acquire the function of MYC through chromosomal translocations, gene amplifications and single nucleotide polymorphisms, causing a variety of metabolic dysregulations." (PMID 36106108, 2022). "Taken together, these results suggest that MYCMI-7 reduces tumor cell growth/viability in a MYC-dependent manner and downregulates the MYC pathway." (PMID 36874405, 2022). "The results showed that genes correlated with ZDHHC7 were significantly enriched in the MYC targets V1/V2, G2M checkpoint, mitotic spindle and E2F targets, which are involved in cancer cell proliferation, tumor growth, and tumor metastasis." (PMID 36286021, 2022).
tumor (continued). "Because c-MYC can directly bind to the CD-47 and PD-L1 gene promoters, inhibiting c-MYC reduces the expression of both genes (CD-47 and PD-L1) and thus improves the anti-tumor immune response." (PMID 37305016, 2022). "Compared with doxorubicin treatment or MYC depletion alone, combing MYC depletion with doxorubicin treatment greatly blunted tumor growth with increased infiltration of macrophages, and enhanced activation of macrophages with M1 phenotype." (PMID 36274066, 2022). "MYC amplification was significantly activated in COCA2, which was associated with tumor cell proliferation." (PMID 36256461, 2022). "The dysregulation of MYC plays a vital role in proliferation and invasion, including tumor initiation and progression in HCC11,12." (PMID 35039581, 2022). "This study demonstrated that high levels of let-7 expression repress tumor growth by regulating MYC expression." (PMID 35806250, 2022). "In HCC, increased BRD4 expression is associated with higher mortality, which correlates with both MYC-dependent and MYC-independent tumor-promoting activity." (PMID 35399501, 2022). "In these studies, MYCMI-6 and Mycro3 were shown to reduce activity or expression of MYC in tumor tissue." (PMID 36874405, 2022). "It has been observed previously that inhibition of endogenous MYC by Omomyc in mouse models induced apoptosis in tumor cells, but only a reduction in proliferation in normal tissues, which was reversible upon MYC reactivation." (PMID 36874405, 2022). "Subgroup B was significantly more active in pathways that facilitate tumor progressions, such as angiogenesis, MYC-mediated targets, and the mTOR signaling pathway." (PMID 36003780, 2022). "Cell proliferation pathways (E2F targets, MYC targets, Mitotic signaling) were also consistently upregulated in tumor-derived T lymphocytes, in line with the observed general expansion of T cells." (PMID 36028490, 2022). "These epigenetic enzymes can be inhibited by a CellCentric developed compound, CCS1477, where administration of CCS1477 was shown to downregulate the expression of AR and MYC, resulting in decreased tumor growth in a 22Rv1 xenograft model of CRPC." (PMID 35547880, 2022). "In consistent with the papers, the pro-tumor actions of c-MYC are further validated in gastrointestinal cancers." (PMID 34623601, 2022). "Statins, including atorvastatin, have been found to block MYC phosphorylation, resulting in tumor-suppressive effects." (PMID 35752695, 2022). "The activation of GNMT expression by androgens would be consistent with a tumor-promoting role, whereas the inhibition by the MYC and PI3K pathways would argue in the opposite direction." (PMID 35197445, 2022). "A dominant-negative form of MYC named Omomyc has been reported for its capability to penetrate in cancer cells, inhibit MYC transcriptional activity and function, and trigger tumour regression." (PMID 36433941, 2022). "Critically, the intravenous administration of miR-138 significantly impedes the tumor growth of MYC-driven mouse model." (PMID 34937878, 2022). "Further investigating the functional status of the immune cells, we found that the tumor immune dysfunction score was significantly lower in the MYC signaling activation group as compared to the MYC signaling inhibition group." (PMID 36299592, 2022). "Intriguingly, HOXA5 overexpression significantly up-regulated the expression of MXD1, a tumor suppressor that can antagonize the formation of MYC-MAX complex, in ECCA cells." (PMID 36167790, 2022). "We show that MYC suppresses STING-IFN signaling in a tumor cell-intrinsic fashion via direct transcriptional repression, thereby blunting immune cell invasion in TNBC." (PMID 36323660, 2022).
tumor (continued). "A previous study confirmed that MYC can directly bind to the promoter of PD-L1 of tumor cells, regulate its transcriptional activity, and participate in tumor immune evasion." (PMID 35978822, 2022). "We observed a good correlation between the MYC activity score and the percentage of tumor cells staining positive for MYC in the Carey training set cases using both the initial gene set and the subset included in our analysis." (PMID 35267654, 2022). "CPE-shRNA loaded exosomes can inhibit malignant tumor cell proliferation via Cyclin D1 and c-MYC suppression." (PMID 35328535, 2022). "Except for CYR61, the expression of YAP, CTGF and MYC were significantly elevated in tumor cells from the diversity-high group." (PMID 35322024, 2022). "To this end, we generated WapCre;Brca1F/F;Trp53F/F;Col1a1invCAG-MycERT2-IRES-Luc/+ (WB1P-MycERT2) GEMMs and investigated tumor growth and immune infiltration at different time points after MYC induction via tamoxifen administration." (PMID 36323660, 2022). "MYC up-regulates global protein synthesis, elevating amino acid and energy consumption, which in the tumour microenvironment stress state induces proteotoxic, MYC-driven apoptosis." (PMID 35311890, 2022). "Nonetheless, our data implies that at least for some tumour types such as those driven by MYC amplification, co-targeting of PI3K, AKT and/or PAK will increase the clinical efficiency and success of CHK1 inhibition." (PMID 36240067, 2022). "Meanwhile, the deletion of c-MYC at the CD4+CD8+ stage of T cell development prevents tumour formation induced by NOTCH1." (PMID 35681778, 2022). "To investigate this, we first examined potential APA of the MYC 3′UTR in tumor and adjacent normal samples from CRC patients (primary tumor stage (T stage) > 2) using 3′ Rapid Amplification of cDNA Ends (3′ RACE) (N = 9)." (PMID 34937878, 2022). "In tumor cells, c-MYC directly activates RBPJκ and subsequent target genes in a NOTCH activation-independent manner, mediated by CDK9, a component of positive transcription elongation factor b (P-TEFb)." (PMID 35215234, 2022). "We describe a previously uncharacterized role for the tumor-suppressive miR-138 as a potent regulator of MYC expression in both CRC and HCC." (PMID 34937878, 2022). "This study uses the GEO database and USCS Xena database to reveal for the first time that the MYC targeting gene MAD2L1 is potentially related to tumor dormancy mechanisms." (PMID 35305591, 2022). "This study evaluated the impact of different dietary protocols (30% CR diet, NCD, and HFD) on the tumour microenvironment and subsequent development and progression of MM in the well characterised transplant Vk*MYC (Vk14451-GFP) C57BL/6J mouse model." (PMID 35908046, 2022). "Oncogenes on ecDNAs, such as MYC, increase tumor cell invasiveness and increase the amount of extrachromosomal DNA in metastatic tumor cells." (PMID 35614494, 2022). "The cancer-related pathways (EMT, MYC target v2, and oxidative phosphorylation pathways) were mainly activated in region 3 of the tumor, located in the peripheral area." (PMID 36434043, 2022). "MYC usually participates in tumor metabolism in combination with other molecules and pathways, such as mTOR and HIF." (PMID 35053485, 2022). "The dysregulation of c-MYC is involved in genome instability, tumor formation, and the maintenance of tumor growth." (PMID 35847930, 2022). "It has been reported that Mxi1 suppressed the transcriptional activity of MYC to repress tumor development." (PMID 35501353, 2022).
tumor (continued). "Another study reported that EZH2 was negatively correlated with the IFN-gamma signaling pathway and positively correlated with the MYC and glycolytic signaling pathways, with respect to tumor growth and aggressiveness." (PMID 36275676, 2022). "As an independent validation of MYC expression, we performed RT-qPCR on isolated tumor and control RNAs." (PMID 36139061, 2022). "Combinatorial treatment of PD-1 inhibitors with decitabine, a DNA methyltransferase inhibitor, elicited the profound anti-tumor effect in MYC-overexpressed TNBC." (PMID 35625867, 2022). "And LDHA was identified as a transcription target of the oncogene MYC and was required for enhanced glycolysis and malignant potential of tumor cells." (PMID 36138435, 2022). "Critically, group 3/4 tumours with KBTBD4 mutations typically lack other gene-specific alterations, such as MYC amplification, indicating KBTBD4 insertion mutations as the primary genetic driver." (PMID 35379950, 2022). "It has been reported that N-MYC and c-MYC have complementary expression, being key factors for the maintenance of pluripotency of tumor cells." (PMID 36551697, 2022). "In summary, using single-cell technology we unraveled murine MYC tumor cell heterogeneity and identified similar gene expression patterns between MYC tumors from different localizations." (PMID 35318328, 2022). "It was indicated that miR-34a-5p/c-MYC/DNMT3a axis regulated PTEN to suppress CRC tumor growth in vivo." (PMID 34623601, 2022). "As a whole, the PP2A holoenzyme is categorized as a tumor suppressor due to its negative regulation of many common oncogenes including c-MYC, BCL2, ERK and AKT." (PMID 35118387, 2022). "To target the IGF2BP1 signaling pathway directly, we utilized the recently published small molecule inhibitor BTYNB which interferes with IGF2BP1 binding to its target mRNAs, such as MYC, thereby impairing tumor cell proliferation." (PMID 35565249, 2022). "Overall, our data expose the role of rSWI/SNF in controlling MYC function and suggest that in addition to MYC, AP-1 is involved in the maintenance of the rhabdoid tumor state." (PMID 35650187, 2022). "Another peculiarity of the Vk*MYC model is the reproduction of cross talk between clonal PCs and the tumor microenvironment." (PMID 35251496, 2022). "At the same time, we noticed that the high expression of POLD2 is also related to MYC targets v2, and the high MYC target score is related to tumor aggressiveness and poor prognosis in metastatic adenocarcinoma." (PMID 36081989, 2022). "The upregulation of MYC in MGUS is clinically relevant, as it is associated with tumor aggression, poor clinical outcomes, and potentially with disease progression." (PMID 36396631, 2022). "The signature genes positively correlated with IFITM3 are characteristic of tumor-promoting functions, including MYC targets." (PMID 35941699, 2022). "Inhibition METTL14 expression results in a significant decreasing of the half-life of MYB and MYC transcripts, thus inhibiting tumor progression." (PMID 35022030, 2022). "By incorporating MYC overexpression and Brca1 disruption into the platform, we substantially accelerate tumor onset and enable modeling of clinically important HR-deficient tumors." (PMID 35082152, 2022). "Upon BRCA1/2-depletion for 24 h, we observed increased numbers of CD8+ T cells that migrated towards the BT-549 tumor cells, which was decreased upon MYC overexpression." (PMID 36323660, 2022). "This highlighted that in the context of MYC, additional tumor immune evasion mechanisms were relevant." (PMID 35760778, 2022). "The deletion of c-MYC at the CD4+CD8+ stage of T cell development prevents tumour formation induced by NOTCH1." (PMID 35681778, 2022). "Upon feeding tamoxifen at seven weeks of age until the time of sacrifice, we again observed that MYC induction reduced immune cell infiltration and shortened tumor latency compared to WB1P tumors, similar to findings with the WB1P-Myc model." (PMID 36323660, 2022).